STEAP1 (STEAP family member 1)
Description:
Does not function as a metalloreductase due to the absence of binding sites for the electron-donating substrate NADPH. Promotes Fe(3+) reduction when fused to the NADPH-binding domain of STEAP4.
Synonyms: PRSS24; STEAP
Tractability: Small molecule: a structure with a bound ligand is known. Antibody: UniProt places it where antibodies can reach, with high confidence; its Gene Ontology location is reachable by antibodies, with high confidence; UniProt predicts a signal peptide or a membrane-spanning region. PROTAC: ubiquitination databases record sites on it. Other modalities: a drug acting on it is in phase 2 or 3 trials.
Target class: Enzyme; Oxidoreductase
Gene: Protein-coding gene on chromosome 7 (90,154,436 to 90,164,829, forward strand). Ensembl gene ENSG00000164647.
Subcellular location: Endosome membrane; Cell membrane
Gene Ontology:
Molecular function: ferric-chelate reductase (NADPH) activity; heme binding; protein binding
Cellular component: membrane; plasma membrane; cell-cell junction; endosome; endosome membrane
Genetic constraint (gnomAD): Loss-of-function variants: 23 observed, 30.92 expected, observed/expected ratio (o/e) 0.74, 90% interval 0.53 to 1.05. The upper end of that interval is the gene's LOEUF score, 1.05, which puts it in group 4 of 6, group 1 being the genes least tolerant of losing a copy. Missense variants: 293 observed, 364.11 expected, observed/expected ratio (o/e) 0.8, 90% interval 0.73 to 0.89. Synonymous variants: 110 observed, 127.71 expected, observed/expected ratio (o/e) 0.86, 90% interval 0.74 to 1.01.
Homologues: Orthologues: chimpanzee STEAP1 (99% identical), macaque STEAP1 (99% identical), dog STEAP1 (91% identical), pig STEAP1 (90% identical), rabbit STEAP1 (89% identical), guinea pig Steap1 (87% identical), rat Steap1 (83% identical), mouse Steap1 (82% identical), tropical clawed frog steap1 (55% identical). Paralogues in human: STEAP1B (72% identical), STEAP2 (47% identical), STEAP3 (42% identical), STEAP4 (35% identical).
Diseases named in the same sentence as STEAP1 in open-access papers:
STEAP1 is named in the same sentence as 76 diseases in open-access papers, as found by Europe PMC text mining. Sharing a sentence is not in itself a finding about the gene and the disease. The quoted sentences say what the papers report.
prostate carcinoma (68 papers, 2010 to 2026). A carcinoma that arises from epithelial cells of the prostate gland. "The results of these therapies are promising, and the diagnostic roles of STEAP1 such as in liquid biopsy in prostate cancer have also been reported recently." (PMID 37909017, 2023). "We evaluated the SwR in tandem with two variants of a CAR that we have developed against STEAP1, a protein highly expressed in prostate cancer." (PMID 36830995, 2023). "To investigate the global impact of STEAP1 loss in prostate cancer, we performed transcriptome profiling of the isogenic 22Rv1 wildtype (wt), 22Rv1 STEAP1 ko, and 22Rv1 STEAP1 ko + rescue cell lines we had previously prepared." (PMID 37041154, 2023). "We then establish the potency and preliminary safety of STEAP1 CAR T cell therapy in relevant preclinical models of prostate cancer but observe recurrent loss of STEAP1 antigen expression as a mechanism of treatment resistance." (PMID 37041154, 2023). "In this study, we identify circulating STEAP1 (six-transmembrane epithelial antigen of the prostate 1)-positive EVs in the plasma of healthy males and prostate cancer patients and evaluate its diagnostic and prognostic significance." (PMID 33589770, 2021). "Our results identify and quantitate STEAP1-positive EVs in plasma and provide rationale for a STEAP1 EV-based liquid biopsy as a diagnostic strategy in prostate cancer." (PMID 33589770, 2021). "STEAP1 is upregulated in prostate cancer and associated with a high Gleason score, seminal vesicle invasion, and biochemical recurrence (BCR)." (PMID 32265985, 2020). "We have previously extended this approach to test the ability of the simian adenovirus and MVA vaccination regime to break tolerance to the tumour associated self-antigen STEAP1 in a mouse model of prostate cancer." (PMID 28537896, 2017). "Furthermore, a recent study revealed that STEAP1-positive extracellular vesicle levels in plasma are significantly associated with prostate cancer diagnoses." (PMID 37909017, 2023). "However, the underlying mechanisms of proliferation and invasiveness triggered by STEAP1 are still controversial, and little is known about the underlying pathways related to STEAP1 in prostate cancer compared to other types of cancer." (PMID 37909017, 2023). "Moreover, high STEAP1 expression is closely associated with poor outcomes in patients with prostate cancer." (PMID 35628495, 2022). "The simian adenovirus, ChAdOx1, and modified vaccinia Ankara virus, MVA, encoding a prostate cancer-associated antigen, the six transmembrane epithelial antigen of the prostate 1 (STEAP1), induced strong sustained antigen-specific CD8+ T-cell responses in C57BL/6 and BALB/c male mice." (PMID 27052571, 2016). "High STEAP1 expression in prostate cancer patients is associated with poor prognosis." (PMID 27104516, 2016). "However, the mechanisms underlying STEAP1 over-expression on prostate cancer remain to be elucidated." (PMID 25053991, 2014). "Thus, STEAP1 antigen loss in prostate cancer promotes not only direct resistance to STEAP1-BBζ CAR T cell therapy but may also limit host adaptive antitumor immunity." (PMID 37041154, 2023). "STEAP1 is much more strongly expressed in tumor cells than in normal tissues and its expression is associated with the malignant phenotype of several types of cancers, including prostate cancer, head and neck squamous cell carcinoma, Ewing family tumors, breast cancer, and melanoma." (PMID 27104516, 2016). "In genitourinary cancers, TDEVs overexpress disease-specific markers such as prostate-specific membrane antigen (PSMA) and STEAP1 in prostate cancer; EGFR and HER2 in bladder cancer; and carbonic anhydrase IX (CAIX) in kidney cancer." (PMID 41459253, 2025). "Future studies are required to investigate the contribution of STEAP1 to the progression of prostate cancer." (PMID 40214422, 2025).
prostate carcinoma (continued). "TDEVs contain tumor-specific molecular markers on their surfaces and within their structure, such as PSMA and STEAP1 in prostate cancer; EGFR and HER2 in bladder cancer; and CAIX in kidney cancer." (PMID 41459253, 2025). "Surprisingly, the authors further demonstrated that STEAP1 knockdown by siRNA reversed the sensitivity of LNCap prostate cancer cells to the apoptotic effects of paclitaxel and cabazitaxel." (PMID 40214422, 2025). "Here, we tested this possibility using human STEAP1 CAR-T cells developed to target prostate cancer." (PMID 40270044, 2025). "STEAP1 (six-transmembrane epithelial antigen of the prostate 1), a prostate cancer-specific membrane antigen, demonstrates expression levels in TDEVs that correlate strongly with tumor burden." (PMID 41459253, 2025). "Specifically, we used CAR-T cells that we have developed for targeting the protein STEAP1 (six-transmembrane epithelial antigen of prostate-1), which is expressed in most prostate cancers and Ewing sarcomas, as well as in subgroups of other cancers." (PMID 40270044, 2025). "A multivariate model combining multiparametric MRI, PSA density, and STEAP1-EV density significantly improves prediction of clinically significant prostate cancer (csPCa), achieving an AUC as high as 0.90." (PMID 41459253, 2025). "Among the STEAP isoforms, STEAP1 and STEAP2 have been identified in EVs associated with prostate cancer." (PMID 40214422, 2025). "STEAP1 is expressed in ~90% of prostate cancers and in sizeable subpopulations of other cancer types such as pancreatic cancer, glioblastoma, lung cancer, bladder cancer, breast cancer, ovarian cancer, leukemia, lymphoma, and head and neck cancer." (PMID 38203757, 2024). "Overall, while NGP-43 represents an innovative approach towards targeting STEAP1 in prostate cancer therapy, further research is needed to determine its efficacy in vivo and potential clinical applications." (PMID 38773495, 2024). "We investigated the ability of the four CAR T cell variants to kill tumor cells by analyzing the induction of active caspase-3 in STEAP1+ target cells (prostate cancer cell line 22Rv1)." (PMID 38203757, 2024). "The Surface Antigen Prostate-6-Transmembrane Epithelial Antigen-1 (STEAP-1) has been identified as a crucial marker for the diagnosis and treatment of prostate cancer." (PMID 38773495, 2024). "NOD scid gamma (NSG) mice were engrafted s.c. on both sides of the hind legs with the human STEAP1-positive prostate cancer cell line 22Rv1." (PMID 38203757, 2024). "A recurring mechanism of prostate cancer relapse and progression after STEAP1-BBζ CAR T cell therapy in our studies was tumor antigen escape." (PMID 37041154, 2023). "STEAP1 CAR T cells demonstrate reactivity in low antigen density, antitumor activity across metastatic prostate cancer models, and safety in a human STEAP1 knock-in mouse model." (PMID 37041154, 2023). "DSTP3086S, a STEAP1-targeting ADC, has shown acceptable safety and potential benefit for patients with STEAP1-expressing, metastatic, castration-resistant, prostate cancer in a phase I trial." (PMID 37909017, 2023). "STEAP1 is expressed in ~90% of prostate cancers and in subgroups of other cancers, such as Ewing sarcoma, lung cancer, bladder cancer, breast cancer, pancreatic cancer, glioblastoma, ovarian cancer, leukemia, lymphoma, and head and neck cancer." (PMID 36830995, 2023). "Although the six-transmembrane epithelial antigen of prostate 1 (STEAP1) was first identified in advanced prostate cancer, its overexpression is recognized in multiple types of cancer and associated with a poor prognosis." (PMID 37909017, 2023). "We subsequently analyzed a larger panel of human prostate cancer cell lines to characterize their native STEAP1 expression by immunoblot analysis." (PMID 37041154, 2023). "STEAP1 was first identified as a prostate-specific-cell surface-antigen that is highly expressed in human prostate cancer." (PMID 37909017, 2023).
prostate carcinoma (continued). "To control for STEAP1 expression in an isogenic manner, we focused on the 22Rv1 human prostate cancer cell line that demonstrates native STEAP1 expression and performed STEAP1 knockout (ko) by CRISPR/Cas9 genome editing." (PMID 37041154, 2023). "Our study also implicates STEAP1 as playing a functional role in regulating cell cycle progression and cellular metabolism in prostate cancer." (PMID 37041154, 2023). "A high level of STEAP1 expression was positively associated with Gleason scores, which is the most reliable histological grading for prostate cancer, and poor prognoses, suggesting that STEAP1 is involved in tumor initiation and progression." (PMID 37909017, 2023). "Further, monoclonal antibodies against STEAP1 were found to inhibit intercellular communication in vitro and suppress proliferation of tumor xenografts in a xenograft model of prostate cancer." (PMID 37909017, 2023). "Similar studies were then performed in the DU145 human prostate cancer cell line that lacks native STEAP1 expression but was engineered to express STEAP1 (DU145 STEAP1) by lentiviral transduction." (PMID 37041154, 2023). "In a phase I study evaluating the ADC targeting STEAP1 in metastatic castration-resistant prostate cancer, there was general consistency between CTCs, the prostate cancer screening antigen PSA, and response on imaging." (PMID 37712425, 2023). "Here, we report broad expression of STEAP1 relative to prostate-specific membrane antigen (PSMA) in lethal metastatic prostate cancers and the development of a STEAP1-directed chimeric antigen receptor (CAR) T cell therapy." (PMID 37041154, 2023). "In both subcutaneous and metastatic xenograft mouse models of prostate cancer, the STEAP1 CAR T cells infiltrated tumors, significantly inhibited tumor growth, and extended survival." (PMID 36830995, 2023). "Further efforts are warranted to clarify the STEAP1-related pathway to develop STEAP1-targeted treatment strategies in prostate cancer." (PMID 37909017, 2023). "STEAP1 is reportedly expressed in more than 80% of the cases of metastatic castration-resistant prostate cancer with bone or lymph node involvement and its expression is elevated in all stages of the disease." (PMID 37909017, 2023). "As mentioned in section 2, STEAP1 has an oncogenic role in multiple types of tumors such as prostate cancer, CRC, HCC, gastric cancer, and lung cancer." (PMID 37909017, 2023). "Six-transmembrane epithelial antigen of prostate-1 (STEAP1) is over-expressed in approximately 90% of prostate cancers." (PMID 36831514, 2023). "A recent study revealed that STEAP1 silencing leads to increased phosphorylation of c-Myc in prostate cancer cells." (PMID 37909017, 2023). "Our STEAP1-BBζ CAR T cells demonstrate substantial antitumor activity against multiple disseminated prostate cancer models both in human-in-mouse and mouse-in-mouse studies." (PMID 37041154, 2023). "The functionality of the JK59 and Dnm-CAR constructs was investigated by using STEAP1+/− prostate cancer cell lines as targets." (PMID 36830995, 2023). "Six transmembrane epithelial antigen of the prostate 1 (STEAP1) is a cell surface antigen for therapeutic targeting in prostate cancer." (PMID 37041154, 2023). "STEAP1 was first described over two decades ago18 and was recognized as being highly expressed in prostate cancer." (PMID 37041154, 2023). "Six-transmembrane epithelial antigen of the prostate 1 (STEAP1) was first discovered owing to its high level of expression in prostate cancer cells." (PMID 37983176, 2023). "Prostate cancer is thus the most investigated type of cancer with respect to STEAP1-targeted therapy." (PMID 37909017, 2023). "Six-transmembrane epithelial antigen of prostate-2 (STEAP2) is also over-expressed in prostate cancer and, similar to STEAP1, it is also pro-tumourigenic." (PMID 36831514, 2023).
prostate carcinoma (continued). "An immunofluorescence-based assay has been developed to evaluate the target antigen of six-transmembrane epithelial antigen of prostate 1 (STEAP1) on CTCs in metastatic castration-resistant prostate cancer patients." (PMID 37712425, 2023). "Six transmembrane epithelial antigen of the prostate 1 (STEAP1) is a highly enriched cell surface antigen expressed in prostate cancer." (PMID 37041154, 2023). "The clinical efficacy of an antibody-drug conjugate targeting STEAP1 in metastatic, castration-resistant, prostate cancer was demonstrated in a phase 1 trial." (PMID 37909017, 2023). "Nevertheless, studies over the last few decades have provided sufficient impetus to investigate STEAP1–4 as potential biomarkers and therapeutic targets for prostate cancer." (PMID 36011027, 2022). "New research into highly expressed proteins in metastatic castration-resistant prostate cancer shows that Six-Transmembrane Epithelial Antigen of the Prostate 1–4 (STEAP1–4) are significant drivers of prostate cancer aggressiveness and metastasis." (PMID 36011027, 2022). "In prostate cancer, STEAP1, STEAP2, and STEAP4 are overexpressed, while STEAP3 expression is downregulated." (PMID 36011027, 2022). "Six transmembrane epithelial antigen of the prostate 1 (STEAP1) was firstly investigated as a potential biomarker in prostate cancer and has been identified to be overexpressed in several types of cancers." (PMID 35313641, 2022). "The studies were conducted with 22Rv1 prostate cancer cells that have variable levels of expression of STEAP1." (PMID 35860008, 2022). "The results confirmed that the prostate cancer cell lines 22Rv1, LNCaP, and C4-2B are STEAP1 positive." (PMID 35860008, 2022). "Another important antigen in the development of prostate cancer is the six-transmembrane epithelial antigen of prostate-1 (STEAP-1), located in intercellular junctions, and overexpressed in all stages of prostate cancer." (PMID 36077739, 2022). "STEAP1 belongs to a family of transmembrane proteins and is upregulated selectively in prostate cancer, with its abnormal expression reportedly related to several oncogenic pathways." (PMID 36046842, 2022). ",18,21,23, 24, 25 Here, we report the development of a CAR against STEAP1 and show that it has significant efficacy against prostate cancer cells in vitro and in vivo." (PMID 35860008, 2022). "In prostate cancer, animal studies have shown that STEAP1 knockdown counters androgen actions, inhibits proliferation, and induces apoptosis in tumor cells." (PMID 35860008, 2022). "STEAP1 is highly expressed in human prostate cancer and is upregulated in a variety of cancers, including lung, bladder, colon, ovarian, and Ewing cancers." (PMID 35346237, 2022). "It shows that STEAP1 is highly expressed on the prostate cancer cell surface and that immune cells infiltrate in the stroma of PCa tumors." (PMID 36011027, 2022). "Other emerging antigen targets of interest in prostate cancer specific ADC development are STEAP1 and Trop-2." (PMID 36046842, 2022). "Here, we describe the development of a CAR against the six-transmembrane epithelial antigen of prostate-1 (STEAP1), which is expressed in ∼90% of prostate cancers, and subgroups of other malignancies." (PMID 35860008, 2022). "Here, eight NSG mice were engrafted s.c. with 22Rv1 prostate cancer cells, and treated with i.v. injection of STEAP1 CAR T cells (N = 3), CD19 CAR T cells (N = 2), or NT T cells (N = 3)." (PMID 35860008, 2022). "STEAP1, in particular, is highly expressed on the plasma membrane of prostate cancer cells and has received significant attention as a potential therapeutic target." (PMID 36011027, 2022). "AMG 509 is a CD3- and STEAP1-specific bsAb-based T-cell engager that is used for the treatment of patients with STEAP1-expressing prostate cancers." (PMID 35628495, 2022).